IL1B (interleukin 1 beta)
Diseases named in the same sentence as IL1B in open-access papers (continued):
Sharing a sentence is not in itself a finding about the gene and the disease.
pneumococcal meningitis (21 papers, 2012 to 2025). An acute purulent infection of the meninges and subarachnoid space caused by Streptococcus pneumoniae, most prevalent in children and adults over the age of 60. "Neutrophil depletion in mouse models of pneumococcal meningitis results in an elevated CSF bacterial load, higher IL-1β, lower TNF-α, and poor survival." (PMID 36873885, 2023). "TNF-a and IL-1b are expressed in hippocampal neurons in vivo in response to lesions and pneumococcal meningitis." (PMID 32087723, 2020). "TNF-α, IL-1β, and IL-6 are the major pro-inflammatory cytokines with early response in pneumococcal meningitis." (PMID 32238192, 2020). "In situ hybridization studies show that in murine pneumococcal meningitis IL-1β and TNF-a mRNA were first upregulated in astroglial cells but at 18–24 h were strongly increased in hippocampal neurons." (PMID 30858801, 2019). "The role of the NLRP3 inflammasome and release of IL-1β have been shown also in pneumococcal meningitis suggesting the involvement of P2X7 receptors in this pathology." (PMID 30814932, 2019). "Although purinergic signaling is essential for NLRP3 inflammasome-dependent IL-1β secretion from macrophages in vitro, is seems to be dispensable under in vivo conditions, namely in pneumococcal meningitis." (PMID 28300164, 2017). "At first, we examined the gene expression of the proinflammatory cytokines TNF-α, IL-6, and IL-1β as representatives of inflammatory mediators in pneumococcal meningitis." (PMID 27057100, 2016). "Collectively, our results demonstrate that S. pneumoniae, especially pneumolysin, induces the activation of caspase-1 and the release of IL-1β in murine pneumococcal meningitis." (PMID 26683708, 2015). "Previous studies showed increased IL-1β levels in brain homogenates of WT mice with pneumococcal meningitis at 30 hours compared to sham." (PMID 23902681, 2013). "Second, IL-1β, which is activated by caspase-1, has been shown to be elevated in the CSF of children with pneumococcal meningitis and correlates with disease severity, a finding that also has been observed in various animal models." (PMID 23902681, 2013). "NLRP3 and AIM2 promote caspase-1 activation and the subsequent conversion of pro-IL-1β into mature IL-1β in pneumococcal meningitis." (PMID 23766853, 2013). "We also measured CSF IL-1β, TNF-α, IL-10 and IL-17A concentrations in 402 patients with pneumococcal meningitis (Appendix p9)." (PMID 41161094, 2025). "Combining penicillin with DNase-1 to treat pneumococcal meningitis accelerates NET degradation, enhances bacterial killing, lowers IL-1β levels, and decreases patient mortality compared to a penicillin regimen alone." (PMID 36873885, 2023). "TNF, a proinflammatory family, can be activated in intracephalic inflammation based on cytokine stress induced by pneumococcal meningitis, such as TNF-α and IL-1β." (PMID 33031061, 2020). "Our present findings are congruous with those of Klein and colleagues, who similarly report lesser increases in IL-1β, but comparable concentrations of CCL2 and IL-6, within the brains of TLR2/4 double GKO mice in a pneumococcal meningitis model." (PMID 31700009, 2019). "Whereas, in experimental pneumococcal meningitis model the animals presented, in the first twenty four hours, elevated levels of TNF-α and CINC-1 in the hippocampus and TNF-α, IL-1β, IL-6 and CINC-1 in frontal cortex." (PMID 23548182, 2013). "In pneumococcal meningitis, adjuvant therapy with an ONOO− scavenger reduces the number of CSF leukocytes concentrations and reduces the brain concentrations of IL-1β and MIP-2." (PMID 23766853, 2013). "IL1-β and IL-18 CSF measurements from pneumococcal meningitis patients showed no altered cytokine responses in different genotype groups." (PMID 27432718, 2016).
pneumococcal meningitis (continued). "IL-6 (median 20 versus 795 pg/ml, P < 0.0001), IL-1β (median 165 versus 939 pg/ml, P = 0.014), and RANTES (median 15 versus 1823 pg/ml, P < 0.0001) were increased at 30 hours post infection in mice inoculated with pneumococcal meningitis as compared to saline inoculated mice." (PMID 22455545, 2012). "IL-1β, IL-2, IL-4, IL-10, IL-12p70, IL-17, RANTES, TNF-α, IL-18 and IL-33 were not significantly altered in the plasma of mice with pneumococcal meningitis compared to sham controls." (PMID 22455545, 2012).
Sjogren syndrome (21 papers, 2009 to 2026). An autoimmune disorder in which immune cells attack and destroy the glands that produce tears and saliva. "We also found increased IL-1β maturation in Sjögren’s syndrome models compared with healthy control lacrimal glands." (PMID 36901740, 2023). "In the current studies, addition of two other proinflammatory cytokines known to be associated with Sjogren’s syndrome pathophysiology, TNF-α and IFN-γ, seemed to potentiate (or synergize) the effects of IL-1β." (PMID 36147586, 2022). "In patients with meibomian gland dysfunction MGD and those with Sjogren’s syndrome, compared with normal participants, the concentrations of tear IL-1α and mature IL-1β were increased, and precursor IL-1β was decreased." (PMID 26605353, 2014). "Interestingly, the NLR Family Pyrin Domain Containing 3 (NLRP3) inflammasome is highly expressed and activated in splenic MDSCs of NOD mice with Sjögren’s Syndrome-like manifestation; thus, these cells produce increased levels of IL-1β." (PMID 38495880, 2024). "In Sjogren’s syndrome, the concentration of caspase 1 in gingival crevicular fluid increased significantly, while the concentration of caspase 1 in peripheral plasma decreased, but the concentration of IL-1β in both parts increased significantly." (PMID 31367484, 2019). "Notably, Sjøgren’s Syndrome (SS) has been associated with overexpression of proinflammatory cytokines, including TNF-α, IL-7, IL-1β, IL-6, IL-10, IL-17, IL-18 and gamma-interferon (γ-IFN)." (PMID 29997338, 2018). "Interestingly, patients with Sjogren's syndrome/sicca symptoms were more likely to have lower IL-8 (odds ratio = 0.89, 95% confidence interval = 0.81 to 0.99) and IL-1β (odds ratio = 0.75, 95% confidence interval = 0.63 to 0.88)." (PMID 19799786, 2009). "In contrast, in Sjögren’s syndrome, NLRP3 activation within salivary gland epithelial cells promotes IL-1β–mediated acinar cell injury and contributes to xerostomia and glandular dysfunction." (PMID 41596738, 2026). "Some of the pro-inflammatory cytokines thought to play an important role in Sjogren’s syndrome pathophysiology are the interferons (IFN), IL-12, IL-18, TNF-α, IL-1β, IL-6 and B-cell activating factor (BAFF)." (PMID 36147586, 2022). "In this study, we investigated the signal transduction pathway through which IL-1β inhibited neurotransmitter release from lacrimal gland nerves of MRL/lpr mice, a murine model of Sjögren’s syndrome." (PMID 24443980, 2014). "Pro-inflammatory cytokines IL-1β, IL-6, IL-17 and TNF-α, as well as chemokines CXCL8, CXCL10, and CXCL13 are significantly elevated in the saliva of patients with Sjögren’s syndrome compared to healthy controls, and that their levels are correlated with the activity and severity of disease." (PMID 38714918, 2024). "Furthermore, interleukin levels such as IL-1a, IL-1b, IL-6, IL-8, TNF-a, and MMP-9 have been detected in Sjogren’s syndrome patients." (PMID 39408709, 2024). "An increased amount of HMGB1 has also been observed in the salivary glands of patients with Sjogren’s syndrome, and HMGB1 may act together with IL-1β and TNF-α in forming a feed-forward loop promoting inflammation." (PMID 28765610, 2017). "Moreover, they found that the protein level of IL-1β was increased in the lacrimal and salivary glands of MRL/lpr mice which represents a mouse model of Sjögren’s syndrome in a disease-dependent manner." (PMID 24443980, 2014).
dysplasia (20 papers, 2011 to 2025). A usually neoplastic transformation of the cell, associated with altered architectural tissue patterns. "In mice, IL-1β is increased following H. pylori infection, and transgenic over-expression of IL-1β using the H/K ATPase promoter caused gastric inflammation and dysplasia." (PMID 25528766, 2015). "IL-1β mice develop inflammation-driven and age-dependent progression of squamous epithelial hyperplasia, dysplasia and squamous cell carcinoma (ESCC) in the esophagus and tongue." (PMID 37543673, 2023). "In dysplasia, the balance shifts yet again back to Th1 with increase in IFNγ IL-1β, IL-2 and IL-8 levels." (PMID 35565378, 2022). "The expression of precursor IL-1β mRNA is correlated with the presence of malignant changes (from normal, to mild, through severe dysplasia to OSCC), and elevated IL-1β expression has been related to lymph node metastasis of OSCC." (PMID 35047997, 2021). "The frequency of IL-1β-positive cells in normal (36.8% ± 6.1%) and dysplasia (80.4% ± 6.3%) samples was significantly lower than that in SCC samples (96.5% ± 3.1%) (P < 0.05)." (PMID 26831400, 2016). "Pro-inflammatory cytokines were expressed by colorectal M1 macrophages during inflammatory hyperplasia (IL-1β, IL-6) and dysplasia (IL-12, TNF-α), thus indicating that MI macrophages have a positive role during the process of carcinoma." (PMID 25434400, 2015). "It is positively regulated by IL-1β in Barrett's oesophagus, and its expression increases along the metaplasia - dysplasia - adenocarcinoma pathway." (PMID 21352563, 2011). "The L2-IL-1β transgenic mice, expressing human interleukin (IL)-1β in the oral, esophageal and forestomach squamous epithelia feature chronic inflammation and a stepwise development of Barrett’s esophagus-like metaplasia, dysplasia and adenocarcinoma at the squamo-columnar junction." (PMID 37543673, 2023). "Another recent study investigated the presence of IL1b, IL8, SAT, and OAZ in the saliva of 34 patients with primary OSCC (T1N0M0/T2N0M0), 20 patients with oral leukoplakia and dysplasia, and 31 matched healthy‐control subjects for prior detection of OSCC." (PMID 38522008, 2024). "Gleber-Nettoet al. performed a study involving 180 patients and reported that among the proteomic markers, IL8 and IL1β concentration was greater in OSCC patients when compared with control and dysplasia patients." (PMID 32399208, 2020). "These mice selectively overexpress human IL-1β in the oral cavity (tongue), esophagus and squamous forestomach and hence also develop esophagitis and dysplasia, but ESCC development was not documented in previous publications." (PMID 37543673, 2023). "Likewise, in our study, the GEJ and gastric cardia/proximal corpus of IL-1β mice showed attenuated total histopathological index scores in the GF state as compared to SPF conditions, though dysplasia (columnar/glandular type) grades were similar in both conditions." (PMID 37543673, 2023).
hematoma (20 papers, 2014 to 2026). A hematoma is a collection of blood from a vascular structure into an extravascular space. "Higher hematoma IL-1β was associated with higher plasma CRP (β-coefficient: 21.0; 95% CI: 4.4-37.5; n = 117 paired samples)." (PMID 42071280, 2026). "The levels of COX-2, tissue-necrosis factor (TNF-α), and interleukin (IL)-1β in the peri-hematoma tissues were measured." (PMID 38981960, 2025). "The results revealed a significant increase in MPO and IL-1β positive cells around the hematoma after ICH, indicating a severe inflammatory reaction." (PMID 38658922, 2024). "In rats subjected to ICH, IL-1β and neutrophils can be observed in the vicinity of the hematoma after 3 h." (PMID 38449739, 2024). "We found that there were significant differences in the expression of P38 MAPK (F = 7.429, p = 0.002), MyD88 (F = 6.973, p = 0.002), HMGB1 (F = 11.753, p < 0.001), and IL-1β (F = 6.821, p = 0.002) around hematoma among the four groups (n = 6 mice/group)." (PMID 35242275, 2022). "The expression level of P38-mitogen-protein kinase (P38-MAPK), myeloid differentiation factor 88 (MyD88), high-mobility group box1 protein (HMGB1), and interleukin-1β (IL-1β) around hematoma was examined by western blotting at 24 h." (PMID 35242275, 2022). "ICH elevated the expression of P38 MAPK, MyD88, HMGB1, and IL-1β around the hematoma when compared with sham surgery at 24 h after ICH or sham surgery (all p < 0.05)." (PMID 35242275, 2022). "We detected the effects of choline diet on the relative expression of P38 MAPK, MyD88, HMGB1, and IL-1β around the hematoma with western blot analysis at 24 h after ICH or sham surgery." (PMID 35242275, 2022). "Immediately after fracture, inflammatory cells infiltrate in the hematoma tissue and secrete pro-inflammatory cytokines such as interleukin-1 beta (IL-1β) and interleukin-6 to recruit macrophages for debris and tissue removal." (PMID 34563248, 2021). "Further, hematoma components such as erythrocyte lysis products are key modulators of brain inflammation and among the pro-inflammatory cytokines, IL-1β is considered as a pivotal inflammatory target after ICH." (PMID 28848394, 2017). "Further, Resveratrol treated mice exhibited improved hematoma resolution with a concomitant reduction in the expression of proinflammatory cytokine, IL-1β after ICH." (PMID 28848394, 2017). "Notably, when the NLRP3 gene is knocked out in ICH rats, the levels of IL-1β and neutrophils surrounding the hematoma decrease, leading to a reduction in brain edema severity." (PMID 38449739, 2024). "The increase in CD36 expression in the perihematomal region is associated with faster hematoma clearance, and reduced CD36 expression increases the production of pro-inflammatory M1 macrophages/microglia mediators, such as TNF-α and IL-1β, thus inhibiting erythrophagocytosis and hematoma clearance." (PMID 35966018, 2022). "Although the expression of P38 MAPK, HMGB1, and IL-1β around the hematoma increased slightly in mice that received a choline diet when compared with those of mice that received a regular diet at 24 h after ICH, the difference was not statistically significant (all p > 0.05)." (PMID 35242275, 2022). "For example, activated nuclear factor-κB (NF-κB) was seen to migrate into the nucleus at 13–48 h after ICH and at the same time, IL-1β and tumor necrosis factor (TNF) levels increased within 1 day after ICH, while downregulation of TNF-αexpression was associated with reduction in hematoma volume." (PMID 30410928, 2018). "We found significantly higher endogenous levels of IL-1β in hematomas from the delayed healing defects, an indication that IL-1β may have a direct influence on the hematoma structures." (PMID 27767056, 2016). "Moreover, IL-1β protein levels were significantly higher in the delayed healing hematomas." (PMID 27767056, 2016). "Effects of NR on (g) IL-1β and (h) TNF-α mRNA levels in the peri-hematoma tissues 24 h following ICH." (PMID 38981960, 2025).
hematoma (continued). "The expression levels of IL-1β, IL-6 and TNF-α in the serum and fracture end hematoma samples of the 48 patients were statistically analyzed, and univariate linear regression analysis was performed." (PMID 37038178, 2023). "The expression levels of the three immune factors (IL-1β, IL-6 and TNF-α) in the fracture end hematoma samples were significantly positively correlated with those in the serum samples (P < 0.05)." (PMID 37038178, 2023). "The relative expression of IL-1β, IL-6, and TNF-α in the fracture end hematoma samples was positively correlated with the corresponding levels of these immune factors in the serum samples." (PMID 37038178, 2023). "Laboratory analysis showed that the relative expression levels of IL-1β, IL-6, and TNF-α in the hematoma at the fracture end were 1.0177, 1.0227, and 1.0095, respectively." (PMID 37038178, 2023). "The levels of IL-1β, IL-6 and TNF-α in the serum and fracture end hematoma samples of the two groups were recorded, and their means were compared by independent sample t test." (PMID 37038178, 2023). "Meanwhile, IL-1β and IL-6 returned to basal levels, and the level of TNF-α in the peri-hematoma region was even lower than that in the control group at 7 days post-ICH, indicating a reaction to the continued immune response." (PMID 36792604, 2023). "For hemorrhagic stroke, NLRP3 upregulation, caspase-1 activation, and IL-1β release occur as early as 3 h post-ICH and intensify gradually in the area around the hematoma from 1 to 5 days." (PMID 35370546, 2022). "In addition, the mRNA levels of IL-1β and TNF-α in brain tissue around hematoma also increased after ICH, which was attenuated by IF." (PMID 35624490, 2022). "Furthermore, the knockdown of Nr4a1 significantly increased the expression of p-NF-κB p65, IL-1β, TNF-α, and MMP-9 with a decrease of ZO-1, occludin, and Lama5 in the peri-hematoma tissue." (PMID 31660977, 2019).